XPA (XPA, DNA damage recognition and repair factor)
Diseases named in the same sentence as XPA in open-access papers (continued):
Sharing a sentence is not in itself a finding about the gene and the disease.
cancer (continued). "XPA is, therefore, an attractive candidate for targeted cancer therapy and the development of small molecules capable of blocking XPA function is a highly exciting field of translational research." (PMID 32235701, 2020). "Polymorphisms of core NER genes such as XPA, XPC, and ERCC can change NER ability by influencing expression and function of important proteins, thereby altering individual susceptibility to cancer." (PMID 27622501, 2016). "XPA expression was detected by immunohistochemistry in cancer tissues from locally advanced NPC patients treated with platinum-based chemoradiotherapy." (PMID 26156020, 2015). "One such important rate-limiting factor is XPA, which has been found to be overexpressed in cisplatin-resistant cancers." (PMID 26317794, 2015). "There have been many studies suggesting that XPA and XPC polymorphisms had a significant effect on the risk of cancer and disease, and they could be a biomarker." (PMID 37510255, 2023). "Variation in XPA's functions may lead to an aberrant NER process and subsequently increase the susceptibility to cancer." (PMID 36118674, 2022). "Importantly, a cancer-associated SNP variant, RASSF1A A133S, exhibits differential XPA binding, inhibits DNA repair and XPA deacetylation, and hyperstabilizes the XPA-RPA complex." (PMID 32235701, 2020). "However, the authors also identified a gene from the NER pathway (XPA gene) that was significantly down-regulated in sensitive cells, indicating that deregulation of this pathway affects PARPi response in both cancer types." (PMID 27374179, 2017). "We found that the preconditioning renders cancer cells more resistant to a subsequent lethal dose of DNA-damaging agent by modulating the sensitivity of XPA association with DNA lesions hence, enhancing NER activity and conferring chemoresistance on cancer cells." (PMID 26317794, 2015). "Given the important nuclear functions of XPA in NER, it is of interest to study the DNA damage-dependent nuclear import of XPA, and also the potential to target protein trafficking as a strategy to improve the sensitivity of cancer cells to chemotherapy agents." (PMID 23861882, 2013). "While lack of functional XPA led to aberrant damage-induced cell death signalling posing a cancer risk, the lack of functional XPB and XPD led to higher damage sustenance, resulting in cell death." (PMID 21176161, 2010). "In a personal context, XPA genetic variations and expression level might once be screened for predicting cancer prognosis leading to additional improvement and a precise approach in cancer treatment." (PMID 32235701, 2020). "Several ongoing approaches aim at targeting the rate-limiting DNA damage incision step of the NER in cancer cells, which is mainly accomplished by the proteins XPG, XPF, XPA, RPA and ERCC140." (PMID 30206212, 2018). "Because of XPA’s crucial functions in NER, the activity of NER and sensitization of cancer cells to chemotherapy can be regulated by transcriptional and post-transcriptional control of the XPA protein." (PMID 23861882, 2013). "At the same time, the NER capacity is a function of the XPA protein levels; therefore, knowledge about the ways of XPA control may find practical applications, such as the manipulation of NER repair activity for successful cancer treatment." (PMID 36496984, 2022). "It is noteworthy that our study was the first time that identified BLM, WRN, XPA, and RAD54L germline P/LP alterations in BTC patients, supporting consideration of expanded genetic testing for those with positive family cancer history or early-onset disease (below 45 years old)." (PMID 36072793, 2022).
cancer (continued). "Additionally, it is known that resistances to platinum-based therapy correlate with high expression of ERCC1 and can be reversed by blocking the interaction between ERCC1 and XPA, which is essential for NER, sensitizing cancer cells to NER substrates." (PMID 29416673, 2018). "Since the DNA damage-induced nuclear import of XPA occurs primarily in S-phase, the inhibition is expected to be specific to replicative cells, typically cancer cells, without interruption of XPA functions in cells in other cell cycle phases." (PMID 23861882, 2013). "As the ERCC5 (XPG) correlations could point to multiple associations, we tested other NER proteins, e.g., XPA and XPC, and found that they generally did not exhibit the same characteristics in these three cancer types, except for XPA in MESO." (PMID 34966786, 2021). "From this point of view, the correlation of up‐regulation of XPA with increased survival time might be applicable to not only CRC but also other types of cancers, the molecular mechanism of which requires further investigations to elucidate." (PMID 29675892, 2018). "This could possibly explain why XPA patients develop cancer while some XPB and XPD patients are not cancer prone and manifest developmental defects of CS and TTD." (PMID 21176161, 2010). "We have previously shown that lack of functional XPA in primary human fibroblasts increased the susceptibility of sodium arsenite- and H2O2-induced genotoxicity while retaining cell viability, posing as a risk factor for cancer in XPA patients." (PMID 21176161, 2010).
tumor (32 papers, 2010 to 2026). "A possible association between XPA expression in tumour tissue and the efficacy of neoadjuvant chemotherapy (NAC) was investigated for locally advanced uterine cervical cancer (UCC)." (PMID 32235701, 2020). "Individual or combined knockdowns were used to determine whether loss of XPA was additive or synergistic with MK2 inhibition for tumor cell killing by cisplatin in culture." (PMID 32807787, 2020). "In tumors, low expression of XPA mRNA and proteins may cause defective DNA damage repair and be related with adverse tumor outcomes such as metastasis and poor pathological differentiation." (PMID 27622501, 2016). "Tumor size (T3-T4) was associated with all polymorphisms of interest except for XPA rs1800975." (PMID 27768589, 2016). "Mutations resulting in the inactivation of tumour suppressor genes, e.g., TP 53, BRCA 1 and 2, and XPA, promote tumour progression." (PMID 40943226, 2025). "We observed a significant association between OS and the expression of six genes (CCNH, MLH3, RAD51C, RPA3, SLK, and XPA) in primary tumor tissues." (PMID 37240218, 2023). "The combination of XPA knockout with AA treatment significantly inhibited tumor growth and prolonged mouse survival compared with the control sgSCR and AA alone treatment." (PMID 36509750, 2022). "Western blot analysis of tumour tissue reveals that NMPNs can decrease the expression of XPA and XPF in the nucleus to inhibit the DNA repair mediated by NER, thus inducing more severe DNA damage." (PMID 36450764, 2022). "The combination of XPA knockout with ENZ treatment significantly inhibited tumor growth and prolonged mouse survival compared to vehicle, sgSCR, or a combination of ENZ and sgSCR." (PMID 36509750, 2022). "Previous studies have shown that HMGB1 can interact with various DNA repair proteins (e.g., RAG and XPA) to address DNA damage repair and to inhibit tumor cell apoptosis." (PMID 30157958, 2018). "CRC patients were stratified according to variables including gender, age, smoking, drinking, TNM stage, and tumor invasion depth, and Mann–Whitney U‐test was performed to explore the differential expression of XPA between groups." (PMID 29675892, 2018). "We observed that in hospital A, there were 2 genes (NEIL1 and XPA) with differential expressions (tumour versus healthy adjacent tissue) collected in PAXgene Tissue System." (PMID 27383461, 2016). "Seven genes out of 13 (CCNH, ERCC2, ERCC6, NEIL1, OGG1, RPA1, XPA) had a significantly different expression in tumour versus normal tissue stored in PAXgene Tissue System." (PMID 27383461, 2016). "As to tumor cells, XPA expression was detected in almost all samples (128/129), and high (H score ≥ 1.4) in 57.4% samples." (PMID 26156020, 2015). "The expression of ALCAM, CN130, DAXX, GAL1, PHF6 and XPA were significantly correlated with tumor grade and stage." (PMID 23819605, 2013). "In addition, co-depletion of MK2 and XPA showed increased DNA damage as measured by the intensity of γH2AX foci, suggesting that co-targeting both MK2 and XPA in tumor cells results in a further abrogation of cisplatin–DNA adduct repair." (PMID 32807787, 2020). "It is tempting to speculate that low HIF-1α levels resulting in low XPA levels may lead to reduced repair of CDDP-induced DNA damage in TGCTs, which could explain the innate CDDP susceptibility of this tumour type." (PMID 32235701, 2020).
tumor (continued). "Interestingly, teratomas (TE), and refractory tumours resected in relapse after chemotherapy, have been shown to be strongly XPA positive." (PMID 31906898, 2020). "Besides, the subgroup with tumor diameter over 4 cm also identified XPA expression as a good indicator for CRC prognosis (HR = 0.49, 95% CI: 0.26–0.91, P = 0.023)." (PMID 29675892, 2018). "Higher XPA levels are particularly common in patients with advanced disease and unfavorable prognostic features, suggesting that increased XPA may contribute to cisplatin resistance, leading to tumor dissemination and disease progression." (PMID 39678373, 2024). "Additionally, the XPA protein level (same as the amounts of proteins that control it) may be a predictor of tumor sensitivity to cisplatin treatment." (PMID 36496984, 2022). "Seven genes passing these filters were involved in various aspects of tumour biology, including cell survival and DNA repair (CASP9, NDRG1, and XPA), mTOR signalling (TSC1), and transcription and RNA processing (ETV6, ISY1, and SMAD2)." (PMID 39660592, 2024). "Intriguingly, the recruitment of downstream effectors of NER to DNA lesion sites, including XPA and XPF, is disrupted, allowing excessive accumulation of the cytotoxic Pt-DNA adducts in cisplatin-resistant tumour cells." (PMID 36450764, 2022). "Other key repair genes such as FEN-1, LIG1, XPA and TOP3A were also found downregulated indicating reduced tumor progression, chemo-resistance, alternative end-joining (Alt-EJ) and nucleotide excision repair (NER)." (PMID 34680264, 2021). "We then randomly selected 26 tumor samples from all OSCC patients and measured XPA protein expression level." (PMID 27622501, 2016). "In primary tumor tissue, the string correlations among CCNH, XPA, and SLK are interesting: CCNH and its correlation with CDK7 and, last but not least, the correlation of CDK7 in strings with RAD51C and XPA." (PMID 37240218, 2023). "Indeed, the expression of XPA and components of the ERCC1-XPF nuclease have been found to be lower in cell lines derived from GCTs compared to those from other tumour types." (PMID 31906898, 2020). "Notably, in vitro cell culture data showed that XPA, ERCC1 and XPF levels are generally lower in GCT cell lines than in cell lines from other tumour types." (PMID 31906898, 2020). "Stratified analysis suggests that this improved prognosis for high XPA expressing tumours is particularly relevant for patients who are over 60 years with RC, without distant metastasis, without tumour deposits, and with a tumour diameter >4 cm." (PMID 32235701, 2020). "Both univariate and multivariate analyses indicated significant correlation between high XPA expression and decreased hazards of death in the CRC cases without tumor deposits (HR = 0.40, 95% CI: 0.21–0.77, P = 0.006, adjusted HR = 0.44, 95% CI: 0.21–0.92, P = 0.028)." (PMID 29675892, 2018).
infection (2 papers, 2021 to 2025). The state of being infected such as from the introduction of a foreign agent such as serum, vaccine, antigenic substance or organism. "A temporal analysis of our data revealed that, during the early stages of infection, there was an increase in XPA and ATM expression, indicating the activation of the nucleotide excision repair (NER) and homologous recombination (HR) pathways, respectively." (PMID 40429613, 2025). "This decrease in the change in inflammatory factors suggested a reduced bacterial infection in the XPa + Infection mice compared with the Infection mice." (PMID 34593766, 2021).
XPA also shares sentences with these, for which no sentence is quoted: gastric cancer (3 papers); head and neck carcinoma (2); liver cancer (2); neurological disease (2); non-small cell lung carcinoma (2); Obesity (2); oral cancer (2); acute respiratory distress syndrome (1); adenoma (1); bacterial infection (1); Brain atrophy (1); breast tumors (1); Cerebellar atrophy (1); cerebro-oculo-facio-skeletal syndrome (1); de Sanctis-Cacchione syndrome (1); digestive system cancer (1); Dystonia (1); endometrial cancer (1); erythropoietic protoporphyria (1); Fanconi anemia (1); head and neck squamous cell carcinoma (1); hereditary cancer syndromes (1); Huntington disease (1); Insulin resistance (1); Joubert syndrome (1); keratitis (1); lipodystrophy (1); Lynch syndrome (1); medulloblastoma (1); metastatic melanoma (1).
A further 12 diseases each share a sentence with XPA in 1 paper.